IDH1 (isocitrate dehydrogenase (NADP(+)) 1)
Diseases named in the same sentence as IDH1 in open-access papers (continued):
Sharing a sentence is not in itself a finding about the gene and the disease.
glioma (continued). "Low ACSL1 expression is associated with a better prognosis in patients with IDH1-mutant glioma." (PMID 39524444, 2024). "In a preliminary study (unpublished) in our laboratory, mutation profiling by Sanger sequencing of hot-spot regions of four glioma-related genes (Idh1, Idh2, Braf, and Egfr) identified point mutations in Egfr gene in 55% (6/11) of the gliomas from chemical-exposed HSD: Sprague Dawley® SD rats." (PMID 38232086, 2024). "Similarly, scRNA-seq analysis of human microglia from five glioma patients also identified a subset of high-grade glioma-associated microglial cells (HGG-AM) in IDH1-WT/SETD2-mutant GBM." (PMID 38665919, 2024). "The present study demonstrates that liquid biopsy may be used in brain tumors to detect IDH1 mutation which represents an important prognostic biomarker in patients with different types of gliomas, being associated to OS." (PMID 38172718, 2024). "However, clinical investigations have demonstrated that patients with IDH1 mutations experience significantly better clinical prognoses than those with wild-type gliomas (median overall survival: 3.8 years vs. 1.1 years)." (PMID 38982076, 2024). "Mutated IDH1 has been described as responsible for the remodeling of the methylome in glioma." (PMID 39123479, 2024). "Therefore, we present the second advantage of our predictive model, which can reflect the mutational status of gliomas, wherein high-risk patients exhibit a lower frequency of IDH1 mutation, 1p/19q co-deletion and MGMT methylation." (PMID 39574472, 2024). "IDH1 mutations are prevalent and associated with better prognosis in gliomas." (PMID 38877400, 2024). "Interestingly, non-canonical IDH1-R132 mutations have an improved prognostic outcome compared to the canonical IDH1-R132H mutation in gliomas." (PMID 39596840, 2024). "Most Grade 4 gliomas showed IDH1 mutations in the present study." (PMID 38893240, 2024). "From a metabolic perspective, in the specific case of high-grade glioma, IDH1-R132H could be viewed as a “therapeutic” mutation." (PMID 39639257, 2024). "Additionally, mutations in the IDH1 gene, common in lower-grade gliomas but also found in GBM, are associated with better treatment outcomes." (PMID 39531784, 2024). "The 5th edition of the WHO classification of CNS tumors classifies these gliomas primarily depending on the isocitrate dehydrogenase (IDH1/2) mutation status into three main types: IDH‐mutant astrocytoma; IDH‐mutant, 1p/19q co-deleted oligodendroglioma; and IDH‐wildtype glioblastoma." (PMID 39026106, 2024). "Furthermore, our research offers plausible molecular explanations for the improved prognosis of IDH1 mutation-type gliomas and their enhanced responsiveness to TMZ." (PMID 38982076, 2024). "Furthermore, this expression is significantly and positively associated with IDH1 gene mutations, which have been linked to a more unfavorable prognosis in glioma patients." (PMID 38529286, 2024). "In the present study, we found that the majority of gliomas (57.2%) with IDH1 mutations were located in the frontal lobe, followed by gliomas affecting multiple sites (33.3%) and temporal or parietal tumors (9.5%), suggesting a potential relationship between IDH1 mutations and tumor localization." (PMID 38172718, 2024). "This may be partially explained by the fact that D-2-HG alters DNA repair pathways, making IDH1-mutated gliomas more sensitive to radiotherapy and genotoxic agents than those without mutations." (PMID 38612890, 2024). "IDH2 ANT relationship suggests functional redundancy with IDH1 mutations in glioma pathogenesis." (PMID 39160568, 2024). "Mutations in IDH1 frequently occur in gliomas (60–80%), AML (20%), and chondrosarcoma (38–86%)." (PMID 39340537, 2024). "Studies have shown that liver disease may lead to dementia through inflammation, and dysbiosis of the oral microbiota is associated with IDH1 mutant gliomas." (PMID 38784036, 2024).
glioma (continued). "Second, expressing mutant IDH1 together with commonly co-occurring mutations in human gliomas could facilitate full malignant transformation of neural stem and progenitor cells and drive gliomagenesis." (PMID 37051530, 2023). "Importantly, efficient generation of autochthonous gliomas in this GEMM required the Idh1 mutant allele." (PMID 37051530, 2023). "This suggests that IDH1 mutation status might be related to genomic instability and combining them together is better for predicting prognosis in glioma patients." (PMID 37547724, 2023). "The proneural subtype is found to be closely linked to amplifications in platelet-derived growth factor receptor A (PDGFRA) and mutations in isocitrate dehydrogenase 1 (IDH1), which causes global hypermethylation and a phenotype called glioma-CpG island methylator phenotype (G-CIMP)." (PMID 38067186, 2023). "Interestingly, IDH1 mutant gliomas (usually associated with secondary gliomas and better prognosis) are closely associated with a CpG island methylator phenotype (G-CIMP)." (PMID 37239035, 2023). "Recently, all gliomas were classified into two groups based on the presence of mutations in the genes encoding for the enzymes isocitrate dehydrogenase 1 and 2 (IDH1/2), which play important roles in cellular metabolism, epigenetic regulation, redox states, and DNA repair." (PMID 37375743, 2023). "Moreover, IDH1‐mutated gliomas are significantly stiffer than IDH1 wild‐type gliomas, regardless of tumor grade." (PMID 36912262, 2023). "Moreover, according to the 2016 and 2021 WHO classification of CNS tumours, gliomas have been classified as IDH1 wild-type (GBM), IDH1 mutations with chromosome 1p19q codeletions (LGG), and IDH1 mutations without chromosome 1p19q codeletions (LGG)." (PMID 37542290, 2023). "Although the cIMPACT-NOW 3 signature was recommended to refine the classification of IDHwt gliomas, we sought to assess whether it also occurred in cases with IDH1/2 mutations and if it impacts upon prognosis in this subgroup of gliomas." (PMID 37973912, 2023). "In particular, 5hmC is significantly downregulated in gliomas, which may be attributed to a mutation in the isocitrate dehydrogenase genes IDH1/2, resulting in either a shortage of TET or the TET cosubstrate α-ketoglutaric acid." (PMID 37964279, 2023). "Interestingly, the authors observed a statistically significant association between low ST3GAL1 expression in low-grade gliomas and IDH1 mutations." (PMID 38067186, 2023). "Furthermore, mutations in the isocitrate dehydrogenase 1 (IDH1) gene are genetic causes of glioma, leading to metabolic changes." (PMID 36814817, 2023). "In this study we are trying to summarize and review the existing methods for the diagnosis of glioma with the terms “IDH1 molecular diagnostic,” “glioma molecular diagnostic,” “1p/19q molecular diagnostic,” “(gene name)” PCR, “glioma NGS panel,” and “(gene name)” NGS panel." (PMID 37908227, 2023). "D2-HG, a crucial metabolite produced by gliomas with IDH1 mutation, could potentially facilitate neuronal fusion by modifying neuronal molecular activity and triggering the mTOR signalling pathway." (PMID 38067243, 2023). "Ninety-six percent PM gliomas from the TCGA cohort harbored mutations in IDH1/2." (PMID 37055795, 2023). "The detection of IDH1 mutations holds great diagnostic and prognostic significance for glioma." (PMID 37414827, 2023).
glioma (continued). "In preclinical patient-derived glioma models, 5-Aza treatment was reported to inhibit tumor proliferation and induce cell differentiation only in tumors that harbor mutations in isocitrate dehydrogenase 1 (IDH1-R132H) gene." (PMID 37894860, 2023). "To disentangle such considerable variability, we used strict inclusion criteria, we adopted the novel WHO diagnostic criteria for gliomas, selecting a unified cohort of IDH1 wild-type glioblastoma and we performed volumetric assessment before any surgical or radio-pharmacological treatment." (PMID 37178276, 2023). "TPL was also reported to have selective cytotoxicity to patient-derived IDH1-mutated glioma cells." (PMID 36969058, 2023). "In this context, mutations in the active site of isocitrate dehydrogenase 1 (IDH1), a catalytic enzyme that produces alpha-ketoglutarate (α-KG) by oxidative decarboxylation of isocitrate, have been related to a better prognosis in glioma patients." (PMID 36986469, 2023). "The role of human glioma IDH1 mutations in regulation of antiviral response is unclear." (PMID 37880243, 2023). "Moreover, IDH1 was selected for further study due to its highest number of mutations and its key role in glioma development." (PMID 36837615, 2023). "Importantly, the expression pattern of GSDMD showed differences according to the status of IDH1/2 mutation and 1p19q co-deletion, indicating detailed molecular characteristics of gliomas and the biological link of the inflammasome." (PMID 37723542, 2023). "Moreover, a comprehensive metabolomics analysis revealed metabolic reprogramming in human gliomas with IDH1 mutations." (PMID 38111705, 2023). "In addition, DNA methylation levels of HIC2 were higher in IDH1 wild‐type glioma patients than in IDH1 mutation glioma patients (p < 0.0001)." (PMID 36650953, 2023). "Consequently, Ag-881 was tested in a phase III clinical trial (INDIGO) in patients up/equal to 12 years of age and with residual or recurrent grade 2 Glioma who carried an IDH1 R132H/C/G/S/L or IDH2 mutation." (PMID 37397394, 2023). "Low-grade and secondary high-grade gliomas frequently contain mutations in the IDH1 or IDH2 metabolic enzymes that are hypothesized to drive tumorigenesis by inhibiting many of the chromatin-regulating enzymes that regulate DNA structure." (PMID 37528157, 2023). "Therefore, IDH2 mutation is considered as equivalent to IDH1 mutation and IDH2-mutant gliomas are conventionally analyzed along with IDH1-mutant gliomas." (PMID 38012788, 2023). "We also analyzed the risk scores of the IDH1 mutant and wildtype glioma patients." (PMID 37867596, 2023). "Notably, Novartis’s IDH305 focuses on IDH1 mutations, and ongoing trials in gliomas and other cancers with IDH1 R132 mutations are active (NCT02381886)." (PMID 38201528, 2023). "However, IDH1-mutated enzymes convert α-KG to 2-hydroxyglutarate, an oncometabolite that induces stem cells’ differentiation into gliomas by inhibition of α-KG-dependent enzymes." (PMID 36986469, 2023). "IDH1 mutations are observed in approximately 34% of glioma tumors." (PMID 37733671, 2023). "In addition, in glioma cells characterized by the presence of the IDH1-R132H mutant, hypersuccinylation causes an upsurge in Bcl-2 levels with consequent apoptosis resistance." (PMID 36980194, 2023). "Three prospective trials (NCT01358058, NCT03180502, NCT02797366, sponsored by NRG Oncology, Sweden and the United States) are conducted regarding proton therapy treating WHO grade 3 glioma with different molecular pathology (IDH1 mutation or 1p/19q codeletion)." (PMID 36755321, 2023). "Phenotype-associated co-regulated 5hmC–5hmC modules and 5hmC–mRNA modules not only are enriched with different molecular pathways that are indicative of the pathogenesis of grade 4 gliomas, but also are of prognostic significance comparable to IDH1 mutation status." (PMID 37580817, 2023).
glioma (continued). "The 5hmC-based prognostic model could offer a robust tool to predict survival in patients with grade 4 gliomas, potentially outperforming existing prognostic factors such as IDH1 mutations." (PMID 37580817, 2023). "In glioma, the mutations occur at the arginine residue at codon 132 in IDH1 (IDH1R132H) and at codon 140 in IDH2, and since the IDH1R132H alteration accounts for 90% of IDH mutations, immunohistochemistry (IHC) evaluation with an IDH1R132H antibody can cover 90% cases of IDH1/2 mutation." (PMID 37158824, 2023). "Besides, several research reported that IDH1 mutation gliomas were likely to respond well to radiation and alkylating chemotherapy." (PMID 37101543, 2023). "In detail, the IDH1 variant was more present in other gliomas than in GBM (p < 0.001)." (PMID 36959606, 2023). "Approximately 80% of GBM and II-III grade gliomas bear somatic mutations in the IDH1 gene." (PMID 38072944, 2023). "Moreover, several studies have discovered that glioma cell subsets after fatty acid-related genotyping are associated with a variety of clinical molecular characteristics (such as age, grade, IDH1 mutation status, 1p19q status, and MGMT status)." (PMID 38111705, 2023). "Gliomas can be classified into several molecular subtypes, many of which have a well-defined profile of driver mutations, such as those in the isocitrate dehydrogenase 1 (IDH1) or 2 (IDH2) genes." (PMID 36932446, 2023). "However, there are few clinical studies focusing on the relationship between radiotherapy efficacy and IDH1 mutation in WHO grade 4 glioma patients." (PMID 37952042, 2023). "Arginine 132 is the hotspot of IDH1 in gliomas and IDH1 R132H mutations are the most predominant mutation which indicates a better prognosis and may be effective for inhibitor treatment." (PMID 37822669, 2023). "IDH-mutant gliomas are genetically defined by the presence of the IDH1 or IDH2 gene mutation." (PMID 37174088, 2023). "Both of IDHmut gliomas carry a hotspot missense mutation in IDH1 or IDH2." (PMID 37932833, 2023). "IDH1 mutations are frequently detected found in low-grade gliomas and secondary glioblastomas." (PMID 38111705, 2023). "Interestingly, another study of in vitro glioma cells demonstrated that IDH1 mutations are associated with lower expression of BMAL1, CLOCK, PER genes, and CRY genes compared to their wildtype counterparts." (PMID 38173841, 2023). "One study recently reported successfully generating several IDH1 mutated glioma cell lines by growing them under serum-free conditions and selecting cells manually based on their tumor cell morphology and separating them physically from the non-tumor associated cells that are IDH-wildtype." (PMID 37920169, 2023). "The time interval between the two operations was significantly longer in patients with low-grade and/or IDH1 mutation glioma than that with high-grade and/or IDH1 wild-type glioma, indicating that the survival benefit of low-grade glioma and/or IDH1 mutation mainly appeared on late recurrence." (PMID 36597096, 2023). "In glioma, mutations in the IDH1 gene impact the synthesis of PC." (PMID 37046844, 2023). "Concerning emerging therapies in glioma epilepsy, the IDH1 mutation may represent a new therapeutic target." (PMID 37071297, 2023). "IDH1 mutations are closely associated with glioma patients' survival." (PMID 37693051, 2023). "Also, a study has found IDH1 can induce DNA hypermethylation that mimics CIMP subtypes in lower grade gliomas, suggesting a causal relationship." (PMID 37234978, 2023). "Nevertheless, the quinolinone-based inhibitors are a promising chemical class for tracer development since they could be used to detect a wide range of IDH1 mutations present in gliomas and generally exhibit favorable PK properties." (PMID 37049661, 2023).
glioma (continued). "Furthermore, IDH1 mutation was an important classification biomarker for glioma 29, The IHC results showed that compared with the IDH1-MT, the expression levels of TRIM21 and β-catenin are significantly upregulated but TIF1γ decreased in IDH1-WT glioma." (PMID 37771771, 2023). "Isocitrate dehydrogenase (IDH) 1 and IDH2 mutations (IDH1/2mt) are frequent in glioma." (PMID 36968138, 2023). "In glioma, a mutation in the IDH1 gene affects the synthesis of PE." (PMID 37046844, 2023). "Using both conventional and edited MRS, we unequivocally assessed the presence of high 2HG levels in a non-glial tumor, encouraging pathologist to perform high throughput molecular screenings that confirmed the presence of the IDH1 mutation and allowed to identify an additional GNAS mutation." (PMID 36941703, 2023). "IDH1/2 mutations are predominantly associated with lower-grade glioma, and it may be the case that endogenous R-2HG production in GSCs suppresses FTO levels, thus reducing oncogene expression and limiting progression by maintaining m6a levels." (PMID 37444417, 2023). "IDH1/IDH2 mutations are associated with a favorable prognosis in patients with glioma and may confer a survival benefit for patients treated with radiation or alkylating chemotherapy [13, NCCN.org]." (PMID 37483495, 2023). "An example is the repression of LDHA expression in gliomas carrying IDH1/2 mutations." (PMID 37546420, 2023). "This case underscores the importance of genetic testing in patients with Maffucci syndrome who present with central nervous system tumors, as well as the need for further research to understand the relationship between IDH1 mutations and the development of gliomas in this population." (PMID 37374260, 2023). "In this study, we compared the early-passage cell cultures derived from patients’ glioma samples, which were different in their IDH1 R132H mutation status supplemented with dissimilar CD44 expression, to find the peculiar nanomechanical signatures characterizing different brain cancer cells." (PMID 36835465, 2023). "To investigate whether mutant IDH1 could enhance the susceptibility of glioma cells to VSVΔ51, we orthotopically transplanted GL261-TRE-IDH1(R132H) cells into immunocompetent mice." (PMID 37880243, 2023). "Furthermore, we performed a stratified analysis based on the WHO classification and IDH1 mutation status of glioma samples in the TCGA and CGGA databases." (PMID 34992215, 2022). "Interestingly, in lower-grade gliomas, the IDH1/2 mutation has more of an impact on miRNA expression than histological and other genomic features." (PMID 35682718, 2022). "It was noted that the IDH1 mutation could suppress CD8+ T cell accumulation in patients with gliomas." (PMID 36233273, 2022). "Therefore, within glioma patients, a mutation in the IDH1/2 gene promotes the growth as well as the progression of glioma." (PMID 35873570, 2022). "IDH1 mutations are associated with a better prognosis in glioma patients." (PMID 36325335, 2022). "The previous studies found that IDH1-mutated gliomas are particularly vulnerable to ABT-263." (PMID 35741587, 2022). "In addition, we revealed that the NF1 and IDH1 mutations were mutually exclusive suggesting NF1 mutation has independent molecular mechanism involved in glioma biology." (PMID 36352461, 2022). "We conclude that patients with Ollier disease which harbor the IDH1 R132H mutation in enchondroma could be at major risk to develop gliomas, compared to those with the IDH1 R132C mutation." (PMID 35884525, 2022). "Results expand our understanding of glioma etiology associated with IDH1 and altered cellular metabolism, identifying new mechanistic links and vulnerabilities, which could be targeted in future clinical trials for glioma IDH-wildtype." (PMID 35877430, 2022). "Thus, pharmacological inhibition of the DNA repair pathway is necessary if radiotherapy demonstrates superior therapeutic advantages in IDH1/2-mutated glioma cells." (PMID 36358574, 2022).